ENSG00000236687 (novel transcript)
Gene: Long non-coding RNA gene on chromosome 9 (131,816,192 to 131,821,276, forward strand). Ensembl gene ENSG00000236687.
Gene Ontology:
Biological process: SRP-dependent cotranslational protein targeting to membrane, signal sequence recognition
Cellular component: signal recognition particle, endoplasmic reticulum targeting